RNU6-537P (RNA, U6 small nuclear 537, pseudogene)
Gene: Small nuclear RNA gene on chromosome 1 (11,152,350 to 11,152,452, forward strand). Ensembl gene ENSG00000253086.
Homologues: Orthologues: chimpanzee U6 (98% identical), mouse Gm23463 (70% identical). Paralogues in human: RNU6-1145P (79% identical), RNU6-1084P (78% identical), RNU6-1209P (78% identical), RNU6-16P (78% identical), RNU6-428P (78% identical), RNU6-510P (78% identical), RNU6-94P (78% identical), RNU6-1159P (77% identical), RNU6-1214P (77% identical), RNU6-1316P (77% identical), RNU6-144P (77% identical), RNU6-208P (77% identical), and 1285 more.